TNF (tumor necrosis factor)
Diseases named in the same sentence as TNF in open-access papers (continued):
Sharing a sentence is not in itself a finding about the gene and the disease.
endotoxemia (continued). "In contrast, the increase in TNF-α, which stimulates the subsequent IL-6 release in response to endotoxemia, is restrained by the splanchnic nerves that provide neural control to abdominal organs including the spleen and involves non-β2- adrenoreceptor mechanisms." (PMID 37535121, 2023). "Thus, specific SUMO1 inhibition unfetters splenic TNFα production and systemic inflammation during lethal endotoxemia." (PMID 37520526, 2023). "Optogenetic DMN stimulation was recently shown to mitigate serum TNF levels during endotoxemia." (PMID 36918973, 2023). "Although it has been demonstrated that a fructose-rich diet increases the hepatocyte production of triglycerides and TNF, the increased gut permeability and consequent endotoxemia may also play a crucial role in this pathogenesis." (PMID 37571424, 2023). "Furthermore, in a rat model of endotoxemia, both compounds reduced TNF-α and IL-6 levels by decreasing NF-κB expression in the lung and liver, in addition to counteracting histopathological changes caused by LPS." (PMID 36364031, 2022). "Only serum TNF-α, IL-8, and endotoxemia could be distinguished between the infected cases versus healthy volunteers and the different severities of infection." (PMID 35406667, 2022). "In addition, some of the evaluated compounds significantly inhibited TNF-α production in a rat model of endotoxemia." (PMID 35930193, 2022). "However, in the mice endotoxemia model, as expected, LPS injection indeed upregulated the expressions of TNF-α, IL-1β, IL-6, and MCP-1 mRNA." (PMID 35370629, 2022). "Additionally, LPS administration in splenectomy mice induced lower serum cytokines (TNF-α and IL-6) than LPS-administered sham mice, perhaps due to LPS tolerance from pre-existing post-splenectomy endotoxemia." (PMID 35163596, 2022). "It is known that the concentration of TNF-α in the blood increases rapidly during endotoxemia." (PMID 36233004, 2022). "Ciliary neurotrophic factor (CNTF) has been shown to protect against LPS induced endotoxemia and reduce TNFα production, and may also increase M2 macrophage differentiation." (PMID 36478877, 2022). "Endotoxemia mortality results exclusively from a systemic inflammatory response characterized by an acute increase in circulating inflammatory cytokine levels (e.g. TNF, IL-6, and IL-1β) from splenocytes and myeloid-derived innate immune cells." (PMID 36264059, 2022). "Similarly, TNFα blockade was effective in preventing lethal endotoxemia in laboratory mice, but the administration of the TNFR75-IgG fusion protein etanercept even increased the mortality of patients with septic shock." (PMID 35903109, 2022). "The inflammatory cytokines TNF-α, interleukin-1ß (IL1ß) and interleukin-6 (IL6) were strikingly increased in LPS- and HpX-treated animals as compared to untreated controls indicating peripheral inflammation caused by endotoxemia or surgical treatment." (PMID 32557202, 2021). "Furthermore, S1-Nal and S1-Nal-Nal can inhibit LPS-induced nitrite oxide and TNF-α production in murine macrophage cells and suppress TNF-α release in endotoxemia mouse model." (PMID 34733262, 2021). "VNS using this implant significantly suppressed TNF levels in endotoxemia." (PMID 33821789, 2021). "Interestingly, compared with LPS treatment group, remimazolam remarkably improved survival rate of endotoxemia mice and decreased the release of LPS-induced inflammatory mediators (such as TNF-α, IL-6, and IL-1β)." (PMID 34867346, 2021). "ROS and RNS induced by oxidative stress may cause tissue damage, and cytokines of TNF-α, IL-1β, and IL-6 can increase the production of ROS and RNS during endotoxemia." (PMID 34065201, 2021). "In the context of lipopolysaccharide-induced endotoxemia, the spleen releases newly synthesized tumor necrosis factor alpha (TNF-α) into the liver via splenic vein; and from there, it enters into systemic circulation, and it is also the primary source of systemic TNF-α in endotoxemia." (PMID 34975827, 2021).
endotoxemia (continued). "During LPS mediated endotoxemia, vagus nerve stimulation has been shown to reduce TNF levels." (PMID 34015044, 2021). "Furthermore, in the prosencephalon, acetylcholine signaling on mAChR M1 receptors (M1 muscarinic acetylcholine receptor) decreases serum TNFα levels in mice with endotoxemia." (PMID 34948222, 2021). "Splenectomy abrogates exercise control of serum TNF-α level in the context of endotoxemia." (PMID 34717724, 2021). "Endotoxemia induces the collapse of the gut and brain barriers, interleukin 1β (IL1β)- and tumor necrosis factor α (TNFα)-mediated neuroinflammatory responses and gliosis, which alter the appetite-regulatory circuits of the brain mediobasal hypothalamic area delimited by the median eminence." (PMID 32106469, 2020). "Proinflammatory cytokine, tumor necrosis factor-α (TNF-α), has a crucial role in the pathogenesis of the AKI caused by endotoxemia, leading to renal inflammatory injury, and acute tubular cell apoptosis presumably by activation of the extrinsic apoptotic pathway." (PMID 33008033, 2020). "However, different results have been reported regarding the diet restriction since, under these conditions, endotoxemia, increased TNF-α and BT, and less Bifidobacteria and Lactobacillus in the ileum were observed after LT." (PMID 33375200, 2020). "In a LPS-induced endotoxemia mouse model, a single intraperitoneal injection of Cl-EE (75–300 mg/kg) could lower circulatory TNF-α, IL-6 and MCP-1 levels." (PMID 31842849, 2019). "(2008) believe that a possible mechanism by which Dex inhibits inflammatory response is that Dex regulates cytokine production, as their study shows that Dex can significantly inhibit the production of pro-inflammatory factors such as IL-6 and TNF-α in endotoxemia mice." (PMID 31545916, 2019). "In addition, serum TNF levels in VAChT−/− mice were significantly higher than in VAChT+/+ mice during endotoxemia (P = 0.009), suggesting that physiological cholinergic transmission in the forebrain regulates peripheral innate immune responses." (PMID 31024522, 2019). "Selective stimulation of acetylcholine action on the M1 muscarinic acetylcholine receptor (M1 mAChR) by central administration of the positive allosteric modulator benzyl quinolone carboxylic acid (BQCA) suppressed serum TNF (TNFα) levels in murine endotoxemia." (PMID 31024522, 2019). "Thus, administration of anti-HMGB1 antibodies inhibited LPS-induced TNF levels in vitro and during endotoxemia." (PMID 30975096, 2019). "Furthermore, leptin treatment decreased the oxidative stress burst in blood and blunted the increase in pro-inflammatory cytokines TNF-α, IL-1β, and IL-6 observed during endotoxemia." (PMID 30618812, 2018). "Furthermore, leptin treatment decreased the oxidative stress burst in the blood and blunted the increased pro-inflammatory cytokines TNF-α, IL-1β, and IL-6 observed during endotoxemia." (PMID 30618812, 2018). "Likewise, in other organs glycine was reported reducing hepatic damage and improve the survival rate of endotoxemia mouse models by regulating TNF-a and IL-10 secretion." (PMID 30050902, 2018). "Notably, the intestinal hyper-permeability was associated with portal endotoxemia and increased hepatic/MAT/intestinal macrophage infiltration, inflammation and corresponding cytokines levels (IL-6, MCP-1, F4/80, TNFα, NFκBp65, TNFRI and TLR4) in NASH-V rats." (PMID 29684027, 2018). "Furthermore, leptin pre-treatment decreased the oxidative stress burst in blood and blunted the increased pro-inflammatory cytokines TNF-α, IL-1β, and IL-6 observed during endotoxemia." (PMID 30618812, 2018). "However, vehicle-treated/endotoxemic rats showed strong increased TNF-α, IL-1β, and IL-6 levels, indicating that a severe inflammatory response was evoked by endotoxemia (respectively)." (PMID 30618812, 2018).
endotoxemia (continued). "These include low HDL and total cholesterol levels, increased proinflammatory cytokines (IL-1, IL-6, TNF-alpha), endotoxemia (lipopolysaccharide), decreased apolipoprotein A-1 level, and hemorrhage and infarction in the adrenal gland due to proclivity to hemorrhage and thrombosis in cirrhosis." (PMID 29201798, 2017). "Furthermore, the capability of the mutated peptides to block LPS-dependent TNF-α and IL-6 secretion by mouse RAW 264.7 macrophages in vitro, as well as mice displaying endotoxemia mice in vivo were also investigated." (PMID 28054660, 2017). "Interestingly, RIPC was shown to down-regulate the serum levels of TNF-α and IL-6 in a rat model of lipopolysaccharide-induced endotoxemia, suggesting that its protective effects were at least in part due to its direct suppression of pro-inflammatory pathways." (PMID 29232398, 2017). "TNF-α is involved in systemic inflammation and plays an important role in endotoxemia." (PMID 28116321, 2016). "Our results indicate that TNF is involved not only in the secretion of agonistic members of the cytokine network in endotoxemia but also in that of an important antagonistic member (i.e., IL-1Ra), assuming that blockade of TNF-α results in a general down-regulation of the cytokine system." (PMID 27316332, 2016). "Although only pups from the CF group showed elevated serum endotoxemia in a previous study, in this study, the 21-d-old offspring of the TF group presented with higher p-NFκB p65 protein levels in the liver and an increased serum concentration of TNF-α." (PMID 26147005, 2015). "To study the specificity and therapeutic potential of miR-511 in mice, we investigated whether miR-511 could protect mice against LPS-induced endotoxemia, a model in which TNF is centrally involved." (PMID 25995337, 2015). "This dual‐LPS injection model for endotoxemia has been shown previously to result in a pronounced increase in the expression of a number of pro‐inflammatory cytokine genes including IL‐1β, IL‐6, and TNFα." (PMID 25903009, 2015). "Due to its inhibitory effect on TNF-α production, we further found that propofol could alleviate cardiac depression and improve survival during endotoxemia in mice." (PMID 25180066, 2014). "Several lines of investigations indicate that alcohol abuse induces endotoxemia, activation of transcription factor NF-κB, and release of a variety of inflammatory mediators including TNF-α, IL-1β, and IL-6 responsible for mounting oxidative stress culminating into liver injury." (PMID 24966470, 2014). "Subsequently, a body of animal and clinical trials reported that dexmedetomodine reduced the level of plasma cytokines, including TNF-α, IL-1 and IL-6, stimulated by endotoxemia, and that dexmedetomidine reduced the mortality rate in endotoxemia-induced shock rat models in a dose-dependent manner." (PMID 24345905, 2014). "This could be very useful for the treatment of conditions involving acute TNF-α elevation such as endotoxemia." (PMID 24776599, 2014). "In conclusion, our findings indicate that glibenclamide could ameliorate myocardial injury and reducing IL-1β and TNF-α possibly through inhibiting Nalp3 inflammasomes and Caspase-1 signaling under LPS-induced endotoxemia in STZ diabetic mice." (PMID 25077824, 2014). "In endotoxemia, hyperactivation of the immune response leads to the excessive production of various pro-inflammatory cytokines (IL-1β and TNF-α) and cellular injury, which also can result in a systemic inflammatory response and eventually lead to multiple organ failure and death." (PMID 25077824, 2014). "The endotoxemia-related decline in Arap1 expression could be recapitulated in cultured mesangial cells by incubation with pro-inflammatory cytokines, such as tumor necrosis factor α and interferon γ." (PMID 23844607, 2013). "Blocking TNF-α reduces myocardial depression induced by endotoxemia." (PMID 23564188, 2013).
endotoxemia (continued). "We assumed that TNFα, IL-6 and IL-10 form an important fraction of gut derived nonbacterial factors, transported via mesenteric lymph and contributing to lung injury during endotoxemia." (PMID 24356325, 2013). "A previous report showed a lower survival rate with a higher TNF-α level during endotoxemia." (PMID 23671873, 2013). "However, cardiomyocytes themselves are the important local source of TNF-α and NO during endotoxemia." (PMID 23691077, 2013). "In summary, these findings suggest that, in a rodent model of laparotomy and endotoxemia, dopexamine at doses within the clinical range can attenuate TNF-α release, tissue leukocyte infiltration, and hence organ injury at doses that do not alter global hemodynamics or regional microvascular flow." (PMID 23531318, 2013). "Likewise, the slow-releasing H2S donor GYY4137, can reduce LPS-induced endotoxemia in mice, as well as the synthesis of pro-inflammatory mediators (such as TNF-α, IL-1β, IL-6, NO and PGE2) by LPS-stimulated RAW 264.7 macrophages in vitro." (PMID 24237604, 2013). "The present study demonstrated that TEAS on ST36 decreased serum TNF-α level in endotoxemia rats." (PMID 23346208, 2012). "After detection using ELISA and Western blot assays, it has also been found that propofol can not only promote the expression of Annexin A1, but also inhibit the phosphorylation level of p38 and release of inflammatory factors (IL-1β, IL-6 and TNF-α) in rats with endotoxemia." (PMID 22164217, 2011). "However, when subjects adopted an acute exercise protocol (75% VO2max), the production of TNF-α elicited by low-grade endotoxemia was inhibited in humans." (PMID 20684772, 2010). "Of note, this subject had a very low cytokine response during endotoxemia (TNF-α level of 169 pg/ml compared with the group mean of 814 ± 133 pg/ml, and IL-6 level of 508 pg/ml compared with the group mean of 1,111 ± 142 pg/ml) and an average cortisol response (0.29 to 0.67 μmol/l)." (PMID 20444270, 2010). "On the other hand, the lack of endogenous IL-10, a prototypic anti-inflammatory cytokine, resulted in increased levels of TNF and enhanced mortality in mouse models of endotoxemia, whereas in models of bacterial infection, endogenous IL-10 impairs the bacterial clearance." (PMID 19454012, 2009). "Gadolinium also upregulates secretion of TNF-α from Kupfer cells in response to endotoxemia." (PMID 20003243, 2009). "To test whether TMP can inhibit the production of TNF-α in vivo we established a transient endotoxemia model in C57BL6/J mice." (PMID 19133137, 2009). "Moreover, NAMPT inhibition reduced intracellular NAD concentration in inflammatory cells and circulating TNFα levels during endotoxemia in mice." (PMID 18493620, 2008). "Thus, it appears that the neutrophil is involved directly or indirectly in increasing TNF-α production in the systemic circulation after endotoxemia." (PMID 17397554, 2007). "This suggests that the presence of neutrophils may alter the production of TNF-α in the lung which then may influence the inflammatory response later in the course of endotoxemia." (PMID 17397554, 2007). "The increases in ET-1 and TNF-α are consistent with a previous investigation employing the endothelin receptor antagonist bosentan, but in contrast to that short-term study, we exposed sheep to 24 hours of endotoxemia." (PMID 15987392, 2005). "Moreover, dobutamine treatment already showed its anti-inflammatory effects through TNF-α and IL-6 reduction in rats with endotoxemia and in septic shock patients; however, in this study, for the first time, we demonstrated that this reduction is associated with NF-κB downregulation." (PMID 38790971, 2024). "Horses from both experimental groups presented clinical signs and hematological changes in endotoxemia, including an increase in heart rate and body temperature, neutrophilic leukopenia, an increase in serum bilirubin, glucose, lactate, and an increase in TNF-α, IL-6, and IL-10." (PMID 38338117, 2024).
endotoxemia (continued). "Similarly, electrical stimulation of the vagus nerve in α7-deficient mice did not lead to a decrease in serum TNF-α levels during endotoxemia, while in wild-type mice, a significant decrease in the level of TNF-α was observed." (PMID 37047495, 2023). "In fact, in a similar model of endotoxemia, one study found that co-treating animals with both α- and β-AR agonists resulted in TNF suppression similar to that in vehicle treated animals, while treating with an α- or β-AR agonist alone increased or decreased TNF, respectively." (PMID 37848937, 2023). "Electrical DMN stimulation significantly reduced pro-inflammatory cytokine levels in the serum (TNF: p = 0.0012; IL-6: p = 0.427) and spleen (TNF: p = 0.0001; IL-6: p = 0.0077), as well as increasing the serum levels of the anti-inflammatory cytokine IL-10 (p = 0.0284) during endotoxemia." (PMID 36918973, 2023). "Furthermore, increased production of inflammatory cytokines to LPS, such as TNF-α and IL-1β, contributed to the failure of intestine barrier integrity in vitamin D deficient and VDR KO mice, leading to bacterial translocation, endotoxemia, and mortality." (PMID 36672703, 2023). "What's more, there was evidence that the occurrence of bacterial/endotoxin translocation in hemorrhagic shock might be accompanied by TNF generation, and endogenous endotoxemia may be involved in the development of multiple organ failure following shock and trauma." (PMID 36819034, 2023). "Likewise, BAM15 also attenuated other parameters of systemic inflammation, as indicated by serum cytokines (TNF-α, IL-6, and IL-10) and serum cell-free DNA (cf-DNA), which might be due to the reduction in endotoxemia and bacteremia." (PMID 35628259, 2022). "Moreover, LA5 improved gut permeability defect (gut leakage) and leaky gut-induced systemic inflammation as indicated by FITC-dextran assay, ZO-1tight junction protein, endotoxemia, colon mucin production (gene expression of muc2) and serum cytokines (TNF-α, IL-6, and IL-10)." (PMID 33737543, 2021). "However, tHGA was shown to be ineffective in rescuing endotoxemic mice from lethality due to its failure in suppressing the overproduction of one of the major inflammatory mediators in endotoxemia, tumor necrosis factor (TNF)-α, thus resulting in multiple organ dysfunctions." (PMID 34531753, 2021). "Therefore, it is plausible that the observed TNF-α response may have been triggered by mild endotoxemia." (PMID 33604558, 2020). "The authors then experimentally showed that CGP-60474 alleviated tumor necrosis factor-α (TNF-α) and interleukin-6 (IL-6) levels in activated macrophages, downregulated the NF-κB activity, and reduced the mortality rate in lipopolysaccharide induced endotoxemia mice." (PMID 32934806, 2020). "The water extract of PQR could significantly inhibit the expression of NOX2, superoxide generation, ERK1/2 phosphorylation and TNF-α in the heart during endotoxemia by inhibiting the signaling pathway of NOX2-ERK1/2-TNF-α, and improve the level of inflammatory factors to improve cardiac function." (PMID 33381041, 2020). "During endotoxemia, high levels of TNF-α and IL-6 could activate JAK2-STAT3 cascade in CNS." (PMID 31213027, 2019). "In addition to positive allosteric modulation of acetylcholine action on M1 mAChR, suppression of serum TNF levels during endotoxemia was also achieved by selective optogenetic stimulation of a subset of basal forebrain cholinergic neurons in the medial septum." (PMID 31024522, 2019). "Thus, we analyzed whether the spleen is essential for the higher serum TNF levels in diabetic mice by performing surgical splenectomy 3 days prior endotoxemia." (PMID 29780390, 2018). "Endotoxemia is a complex syndrome defined by an uncontrolled activation of the innate immune system, with initiation of the complement pathway and high amounts of circulating pro-inflammatory tumor necrosis factor-alpha (TNF-α), which induces multiple organs failure." (PMID 28659918, 2017).